TRAJ31 (T cell receptor alpha joining 31)
Description:
J region of the variable domain of T cell receptor (TR) beta chain that participates in the antigen recognition. Alpha-beta T cell receptors are antigen specific receptors which are essential to the immune response and are present on the cell surface of T lymphocytes. Recognize peptide-major histocompatibility (MH) (pMH) complexes that are displayed by antigen presenting cells (APC), a prerequisite for efficient T cell adaptive immunity against pathogens. Binding of alpha-beta TR to pMH complex initiates TR-CD3 clustering on the cell surface and intracellular activation of LCK that phosphorylates the ITAM motifs of CD3G, CD3D, CD3E and CD247 enabling the recruitment of ZAP70. In turn ZAP70 phosphorylates LAT, which recruits numerous signaling molecules to form the LAT signalosome. The LAT signalosome propagates signal branching to three major signaling pathways, the calcium, the mitogen-activated protein kinase (MAPK) kinase and the nuclear factor NF-kappa-B (NF-kB) pathways, leading to the mobilization of transcription factors that are critical for gene expression and essential for T cell growth and differentiation. The T cell repertoire is generated in the thymus, by V-(D)-J rearrangement. This repertoire is then shaped by intrathymic selection events to generate a peripheral T cell pool of self-MH restricted, non-autoaggressive T cells. Post-thymic interaction of alpha-beta TR with the pMH complexes shapes TR structural and functional avidity.
Gene: T-cell receptor joining (J) gene on chromosome 14 (22,510,968 to 22,511,024, forward strand). Ensembl gene ENSG00000211858.
Subcellular location: Cell membrane
Gene Ontology:
Cellular component: plasma membrane